ALB (albumin)
Diseases named in the same sentence as ALB in open-access papers (continued):
Sharing a sentence is not in itself a finding about the gene and the disease.
bacterial infection (92 papers, 2010 to 2025). "In this study, the first postoperative albumin level was collected, which was associated with multi-drug-resistant bacterial infection." (PMID 38558019, 2024). "Univariate analysis revealed that bacterial infection was associated with female, age (≥ 50 years old), preoperative albumin (≤ 30 g/L), operation duration (≥ 400 min), intraoperative blood loss (≥ 3000 ml) and postoperative ventilator support." (PMID 37525234, 2023). "In this study, we found that GI bleeding, bacterial infection, age, ALB, TBIL, BUN, PTs were the independent risk factors for HA-AKI in ACLF patients." (PMID 35545763, 2022). "Gastrointestinal bleeding and low serum albumin which plague the LD patient population are known risk factors for bacterial infection in cirrhotics." (PMID 28865456, 2017). "Albumin is an important component of human body, which has a variety of functions, such as extracellular antioxidants, buffers, immunomodulators and antidotes, and can alleviate inflammation caused by bacterial infection." (PMID 33407152, 2021). "The baseline CPS levels were negatively correlated with serum albumin levels (r = −0.425, P < 0.05), suggesting that bacterial infection might be associated with hepatic function in cirrhotic patients." (PMID 34263080, 2021). "Hepatic damage associated with parasitic and bacterial infections may suppress the metabolic activity of the liver, thus decreasing albumin and globulin concentrations in infected goats." (PMID 34475695, 2021). "ALB is an important substance to maintain plasma colloid osmotic pressure, but bacterial infection in the throat can cause local vascular permeability to increase, lead to vasodilatation and exudation of the serous fluid, and finally result in hyperemia, pain, and even thickening of the mucosa." (PMID 33101439, 2020). "However, there are studies that state that some drugs used to treat bacterial infections in the urinary tract, such as sulfonamides, can potentially cause harm in the case of lower bilirubin levels because they displace bilirubin from albumin, thereby increasing the free bilirubin fraction." (PMID 39475918, 2024). "This study also evaluated the anti-inflammatory activity of FN33 AMP by assessing its ability to prevent heat-induced albumin denaturation, as inflammation plays a crucial role in bacterial infections." (PMID 40422799, 2025). "Albumin influences the host’s defense mechanisms against bacterial infection through the complement function and defensin production." (PMID 38907196, 2024). "Albumin is the second component of NPAR and is linked to the development and severity of bacterial infections." (PMID 38561807, 2024). "Our study showed that compared with the decompensated group, the recompensated group had fewer ACLF patients precipitated by bacterial infection, and the patients had higher Hb, ALB, and serum sodium and lower WBC and INR." (PMID 37726716, 2023). "It has been investigated that chlorine compounds produced by activated neutrophils in viral or bacterial infection lead to oxidative modification of albumin and the formation of AOPPs57,58." (PMID 36396711, 2022). "The multivariate logistic regression model (KP-AKI) for predicting the occurrence of HA-AKI were age, gastrointestinal bleeding, bacterial infections, albumin, total bilirubin, blood urea nitrogen and prothrombin time." (PMID 35545763, 2022). "In this study, we postulated that albumin protects macrophages from the damage of bacterial infection." (PMID 34571946, 2021). "On univariate analysis, Child-Pugh scores ≥ 7, albumin ≥ 3.5 g/dL and plasma M2BPGi levels ≥ 6 C.O.I were significant predictors for occurrence of bacterial infection within five years." (PMID 34648567, 2021). "The decrease in circulating globins and serum albumin was also observed in brook trout following bacterial infection and ascribed to a reduction in transcription and potentially additional catabolism induced by the inflammation." (PMID 20602791, 2010).
bacterial infection (continued). "A lower albumin/ascitic fluid protein ratio may indicate a reduced ability of the ascitic fluid to resist bacterial infection." (PMID 41353185, 2025). "Indeed, in Atlantic salmon, bacterial infection and development of coldwater vibriosis have been shown to reduce serum albumin, cholesterol and alkaline phosphatase, and increase HSI and liver water and lipid content, as well as plasma ALAT." (PMID 41311413, 2025). "Upon comparison to sputum from other inflammatory conditions like bacterial infections and CF, a common set of proteins that include acute phase blood plasma proteins like albumin, alpha-1-acid glycoprotein 1, neutrophil proteins, and PADI enzymes were found to be elevated." (PMID 34139362, 2021). "The bivariate analysis showed that age, hepatic encephalopathy, bacterial infection, the SpO2/FiO2 ratio, the neutrophil count, the sodium level, albumin, the total bilirubin level, the creatinine level, and prothrombin time were significant predictors of in-hospital mortality." (PMID 34670501, 2021). "Furthermore, patients with albumin, intravenous immunoglobulin, certain antibiotics, bacterial infections, or renal replacement therapy with cellulose membranes may have false positive results." (PMID 40506974, 2025). "However, despite its advantages, the MELD score incorrectly predicts mortality in about 15–20% of patients due to the score not including major cirrhotic complications such as bleeding, bacterial infection, HE, and albumin levels, which induce a poor prognosis for patients." (PMID 38201324, 2023). "Thus, we conjectured that albumin supplementation might mitigate bacterial infection in patients with CLDs." (PMID 34571946, 2021). "Multivariate analysis identified total bilirubin, albumin, white blood cell count, and NLR as independent predictors of HA bacterial infections." (PMID 39296886, 2024). "However, the lymphocytes (LYM), hemoglobin (HGB), ferritin, aspartate aminotransferase (AST), albumin (ALB), lactic dehydrogenase (LDH), and activated partial thromboplastin time (APTT) were greater in SFTS than in bacterial infection." (PMID 39688402, 2025). "In decompensated cirrhosis complications, such as hepatic encephalopathy and non-SBP bacterial infections, short-term albumin shows limited clinical or survival benefits." (PMID 38139434, 2023). "Conversely, lymphocytes, hemoglobin, and albumin values (all P < 0.0001) were significantly lower in patients with bacterial infections than in those without." (PMID 37101265, 2023). "Serum albumin is a negative acute-phase protein during inflammatory reaction by bacterial infection." (PMID 31253199, 2019). "Interestingly, it has been shown that in states of inflammation and bacterial infection TRF may exhibit earlier changes and higher sensitivity than ALB." (PMID 40566087, 2025). "In addition, AgNPs treatment did not alter the urea and albumin concentrations, where they maintained normal levels upon treatment and after bacterial infection." (PMID 32793561, 2020). "However, the rabbits that were sensitized to albumin did not develop chronic inflammation without bacterial infection." (PMID 28717520, 2017). "An update of the ICA criteria (2007) stated that active bacterial infection—in the absence of shock—is not an exclusion criterion for HRS diagnosis and recommended the use of albumin over saline for plasma expansion." (PMID 34131658, 2021). "Furthermore, the INFECIR-1/-2 an ALB-CIRINF trials (investigating the use of albumin in patients with ACLD and non-SBP bacterial infections) found no significant impact on kidney dysfunction." (PMID 34131658, 2021). "The improvement in circulatory dysfunction and effective hypovolemia in non-SBP bacterial infection were confirmed very recently by the INFECIR-2 study, which showed that albumin, at the same dosage as reported in the previous studies, increased mean arterial pressure and lowered PRA [48•]." (PMID 32837825, 2020).
infectious disease (84 papers, 2008 to 2025). A disorder directly resulting from the presence and activity of a microbial, viral, or parasitic agent in humans. "Low gamma gap levels mean week immunological background, especially for infectious diseases, and this study suggested low albumin levels further elevated its risk." (PMID 41248155, 2025). "Liver injury caused by emerging infectious diseases is usually characterized by elevated transaminase and bilirubin levels and decreased ALB levels, but the specific manifestations vary according to the pathogen." (PMID 41169390, 2025). "In the present study, we examined age, disease severity, and laboratory data on admission, including albumin, in patients admitted to our emergency department with infectious diseases in order to identify risk factors for functional decline at discharge." (PMID 33374807, 2020). "In the present study, we show that maintenance HD patients with reduced serum NGAL levels were prospectively associated with decrease in serum albumin levels, and had an increased likelihood to require admission for the treatment of infectious diseases." (PMID 26161663, 2015). "The association between VA deficiency and high aflatoxin B1 albumin (AF-ALB) levels may result in impairment of the host immune response, which increases susceptibility to infectious diseases." (PMID 39149555, 2024). "Associations of serum albumin levels with development and severity of infectious diseases may be sufficiently explained by the effects of systemic inflammation on albumin kinetics making low serum albumin levels a surrogate marker." (PMID 33925831, 2021). "Our findings indicated that APACHE II score, qSOFA score, serum albumin level, and underlying respiratory or infectious disease were risk factors for mortality and APACHE II score, serum total bilirubin level, and admission diagnosis were associated with ICU LOS." (PMID 34356231, 2021). "This underlines that the combination of low albumin levels with underlying disease or confounder effects might have driven the associations between reduced albumin levels and infectious diseases." (PMID 34154403, 2021). "However, the risk of allogeneic infectious diseases exists, and the supply may be unstable because human serum albumin is derived from human blood." (PMID 34201225, 2021). "SHAP analysis revealed that ALB (albumin) was the most influential predictor of mNGS test results, which aligns with the pathophysiological characteristics of infectious diseases." (PMID 40302920, 2025). "Infectious diseases often lead to reduced ALB levels, and our results also observed that severe and critically ill patients had lower ALB levels than non-severe patients." (PMID 39628680, 2024). "The predictive usefulness of the BUN-to-ALB ratio (BAR) for some infectious disorders has been highlighted by research, and the mortality prediction of the BAR is substantially higher than that of BUN and ALB." (PMID 38806039, 2024). "Low serum albumin levels reflect impaired liver function during infectious diseases, as inflammatory factors can impede albumin synthesis." (PMID 38376000, 2024). "C-reactive protein-to-albumin ratio (CAR) is an independent risk factor in cardiovascular, cerebrovascular, and infectious diseases." (PMID 36006278, 2022). "In this study, after adjusting for age and sex, APACHE II score, qSOFA score, serum albumin level, and diagnosis on ICU admission such as respiratory or infectious disease were risk factors for mortality among ICU patients." (PMID 34356231, 2021). "Infectious diseases can be characterized by increased serum levels of cell-free DNA, reflecting NETosis and decreased levels of albumin; however, the degree of inverse correlation still needs to be investigated." (PMID 33925831, 2021). "Generally, all of these genes played vital roles in the inflammation and immune-related process, which indicated the potentially important roles of albumin in colostrum and serum in resistance to infectious diseases." (PMID 33255903, 2020).
infectious disease (continued). "All variables incorporated in the prediction rule (age, sex, serum Cr, serum albumin, total cholesterol, and weekly renal Kt/V) are associated with PEW, emphasizing a strong association between PEW and the risk of infectious disease-related death." (PMID 30893369, 2019). "Serum levels of albumin, pre-albumin and number of lymphocytes were significantly lower in blood of aged patients with infectious diseases in acute phase compared to the control healthy aged probands." (PMID 20716329, 2010). "The SHAP-derived rankings identified albumin, procalcitonin, blood culture, disease type, and sample type as the most influential features—findings that are both clinically plausible and consistent with infectious disease pathophysiology." (PMID 40302920, 2025). "Thus, this study reinforces the findings that the serum ALB concentration is a marker of disease severity in patients with COVID-19 infection as well as in those with other infectious diseases." (PMID 40399692, 2025). "The relationship between serum albumin levels and the onset and severity of infectious diseases may be due to the effects of inflammation on albumin levels." (PMID 38561807, 2024). "In addition to scores used to determine and predict the severity of infectious diseases, ratios such as fibrinogen to albumin ratio are also being investigated." (PMID 38550447, 2024). "Serum protein electrophoresis is widely used in veterinary medicine to quantify albumin and globulin fractions and identify their changes in concentration, which could be supportive of the inflammatory status or indicative of infectious diseases." (PMID 37889653, 2023). "Protein electrophoresis has been widely used in human and veterinary medicine to evaluate albumin and globulin fractions (α‐, β‐, and γ‐globulins) for assessment of ongoing inflammatory processes like infectious disease, parasitism, trauma, and/or poor nutritional plane." (PMID 35437805, 2022). "Serum albumin, a value measured in hospitalized patients, has a role as acute phase reactants and has been proposed as a reliable predictor of outcomes in critically ill patients with infectious diseases." (PMID 34441006, 2021). "Albumin fusion with GM-CSF represents a promising strategy for the control of chronic lung tuberculosis infections and serves as a novel therapeutic vaccination platform for other infectious diseases and malignancies." (PMID 32382128, 2021). "For instance, the roles of albumin, selenium, and electrolytes deserve further exploration, and the recognized importance of vitamin A in mounting an immune response to infectious diseases urgently merits further studies." (PMID 31845848, 2020). "In the present study, Tx patients had higher mortality mainly due to infectious diseases, which could be partially explained by the lower albumin levels and BMI observed in this group on the time of admission in the PD program." (PMID 31978190, 2020). "A new formulation of the live-attenuated varicella vaccine Varilrix (GSK) produced without human serum albumin (HSA) was developed to minimize a theoretical risk of transmission of infectious diseases." (PMID 30732648, 2019). "Since albumin is derived from human plasma, it is relatively expensive and may facilitate transmission of infectious diseases." (PMID 30202516, 2018). "For example, while other inflammatory indices such as the neutrophil-to-lymphocyte ratio have been linked to adverse outcomes in infectious diseases, the CRP/albumin ratio may capture a broader pathophysiological profile by integrating markers of inflammation with baseline physiological reserve." (PMID 40872333, 2025). "Furthermore, the potential risk of transmission of communicable diseases or viruses from the human serum albumin component is not completely absent." (PMID 30157821, 2018). "The albumin-to-globulin ratio (AGR) has been used to predict severity and mortality in infectious diseases." (PMID 35601226, 2022).
infectious disease (continued). "Neutrophil–albumin ratio (NAR), which is the ratio of neutrophil count to albumin value, shows potential in assessing the severity of inflammation and predicting the prognosis in infectious diseases." (PMID 41036136, 2025). "Total protein was significantly higher in infectious diseases than in CNSL and demyelinating diseases (p = 0.0391 and p = 0.0377, respectively), although serum albumin (Alb) was significantly lower in CNSL than in infectious and demyelinating diseases (p = 0.0002 and p = 0.0015, respectively)." (PMID 37501501, 2023). "The prognostic function of the albumin-to-globulin ratio (AGR) has been studied in several other pathologies, such as those of small cell lung cancer, hepatocellular carcinoma, heart failure, and infectious diseases." (PMID 35601226, 2022). "Other human clinical trials in lung Mycobacterium avium complex patients with HET for six months resulted in weight gain and increased serum albumin value without a tendency for infectious disease to exacerbate on chest radiograph." (PMID 30071688, 2018). "One hundred and seventy-eight HIV infected children aged 15 years and below were recruited from the Paediatric Infectious Disease Clinic of Aminu Kano Teaching Hospital (AKTH), Kano, to determine the prevalence of persistent microalbuminuria using the albumin creatinine ratio (ACR)." (PMID 24724027, 2014). "Moreover, we excluded diseases such as malignancy, hematological proliferative disease, ongoing steroid or immunosuppressive therapy, and active infectious diseases, which have been shown in the literature to affect inflammatory or nutritional (NLR, LMR, albumin, TC) parameters that compose the NPS." (PMID 39518572, 2024). "Our findings support the role of albumin as a negative APP in cats seroreactive and infected (currently or recently) by pathogenic leptospires, as it has been previously reported in other inflammatory or infectious diseases in the species." (PMID 37679743, 2023). "Careful screening is done by the manufacturers to reduce the likelihood of transmission of infectious diseases such as HIV, Hepatitis B and C. To date there have been no documented cases of disease transmission linked to human serum albumin usage at [Clinic 55]." (PMID 32908955, 2020). "As a sensitivity analysis, of 1400 patients admitted with non-infectious diseases and discharged alive, we analyzed 968 patients with recorded BI at discharge and found significant differences in age (p < 0.001), male sex (p = 0.013), APACHE II (0.036), and albumin (p < 0.001)." (PMID 33374807, 2020). "The correlation between low levels of albumin and LOS applies to the wards of surgery, infectious diseases, medicine, orthopedics and urology; in contrast, the rare measurement of albumin in gynecology and obstetrics unit does not allow to achieve statistical significance." (PMID 28344803, 2017). "ALB and LDH has been usually used separately to assess severity, however no study assessed their prognostic efficacy as a ratio in infectious diseases." (PMID 36614820, 2022).